MSLN (mesothelin)
Diseases named in the same sentence as MSLN in open-access papers (continued):
Sharing a sentence is not in itself a finding about the gene and the disease.
breast carcinoma (continued). "Percentages of breast cancer with MSLN overexpression varied between studies, probably due to different subtypes being analyzed." (PMID 26172299, 2015). "Within the subset of estrogen receptor (ER) positive (N = 4,906) and within the subset of human epidermal growth factor 2 (HER2) positive (N = 1,580) breast cancer samples the MSLN amplification rate was 3% and 7%, respectively." (PMID 26172299, 2015). "We observed a predicted MSLN amplification rate of 10% in the total set of breast cancer samples (N = 7,270)." (PMID 26172299, 2015). "In the breast cancer specimens, MSLN showed variable staining intensity and percentage in the tumors cells." (PMID 25506917, 2014). "Ectopic expression of the MSLN gene in a human breast cancer cell line promoted cell survival and anchorage-independent growth invitro." (PMID 25118887, 2014). "Taken as a whole, our study demonstrates that the combined use of Carboplatin, Paclitaxel and MSLN inhibition may synergistically inhibit breast cancer liver metastasis, offering therapeutic benefit to TNBC patients with liver metastasis." (PMID 41513618, 2026). "Similarly, in breast cancer models, MSLN also inhibits Bim-mediated apoptosis via the ERK signaling pathway, further enhancing the resistance of tumor cells to chemotherapy during metastasis." (PMID 41400642, 2025). "Thuwajit's team further explored the subtype specificity of MSLN expression in breast cancer." (PMID 41400642, 2025). "Novel approaches to CAR-M-based breast cancer treatment may be provided by ongoing clinical trials on CAR-M targeting MSLN." (PMID 39755633, 2025). "Clinical experiments on CAR-M targeting MSLN for breast cancer are underway and may provide new methods for the treatment of breast cancer using CAR-M." (PMID 38680498, 2024). "Another study investigating the role of exosomes in breast cancer treatment indicated that the utilization of mesothelin (MSLN)-targeted CAR-T cell-originated exosomes successfully inhibited the growth of MSLN-positive cancer cells in triple-negative breast cancer." (PMID 36406206, 2022). "The CAR-T cells targeting MSLN in breast cancers mainly focus on TNBC." (PMID 35414783, 2022). "The expression of mesothelin correlates with a poor prognosis in patients with breast cancer." (PMID 34715925, 2021). "Overexpression of mesothelin was shown to promote invasion and metastasis in breast cancer cells." (PMID 32793490, 2020). "Breast cancer targeting using CAR technology has been well documented with studies reporting the generation of CAR for breast cancer-associated tumour antigens such as carbonic anhydrase IX, ERBB2, mesothelin, EGFR variant III (EGFRvIII), carcinoembryonic antigen (CEA), and Mucin-1 (MUC-1)." (PMID 28885562, 2017). "Examples of other TAAs that could be used in combination with ERBB2 in targeting breast cancer include melanoma-associated antigen-A4 (MAGE-A4), mesothelin, and MUC-1." (PMID 28885562, 2017). "For example, MSLN positivity has been described in 38% to 69% of lung adenocarcinomas, 17% to 100% of pancreatic adenocarcinomas, 2% to 68% of colorectal carcinomas, 55% to 100% of serous carcinomas of the ovary, 21% to 78% of gastric adenocarcinomas, and 3% to 36% of breast carcinomas." (PMID 33917081, 2021). "Some years later, MSLN was revealed as broadly overexpressed in many others cancer indications, including squamous cell carcinomas of the esophagus, pancreas, lung, stomach, bile ducts, colorectal, and breast cancer, where its expression correlates with a worse prognosis." (PMID 33418877, 2021). "Importantly, targeting MSLN high expressed liver metastasis breast cancer with a Paclitaxel/Carboplatin combination displayed a significant anti-metastatic effect, suggesting that targeting MSLN-EGFR-ERK signaling could be an effective strategy for treating TNBC liver metastases." (PMID 41513618, 2026).
breast carcinoma (continued). "For breast cancer normal-tumor differentiation, CXCL14, MSLN, LCN2, and MED1 emerged as significant predictors, supported by evidence of their differential expression and involvement in tumor progression." (PMID 41139924, 2025). "In a retrospective study of breast cancer, 42.3% of TNBC patients were found to have positive MSLN expression." (PMID 41400642, 2025). "For HER2-positive breast cancer, the HSV-based OV R-LM249 selectively infects and kills HER2-overexpressing cells For HER2-negative tumors, mesothelin (MSLN) is a promising target." (PMID 41000377, 2025). "Yet, despite encouraging preclinical results in breast cancer models targeting HER2, MUC1, or mesothelin, single-target CAR-T cells have demonstrated minimal clinical efficacy in solid tumors, including breast cancer, with objective response rates below 13%." (PMID 41348261, 2025). "One of these antigens is mesothelin (MSLN), which is overexpressed in many solid tumors and has been shown to be a promising target for CAR-T cell treatment in breast cancer." (PMID 38892913, 2024). "This work suggests a tailored immunotherapeutic strategy to regulate TAM-mediated immune reactions in breast cancer subtypes by epigenetically adjusting the expression of CD80 and MSLN by modifying MALAT-1 and HOTAIR." (PMID 38511067, 2024). "Since mesothelin plays a role in cancer metastasis in association with CA125, we herein examined the expression of mesothelin and CA125, and the clinicopathological meaning and prognosis of the co-expression of mesothelin and CA125 in breast cancer." (PMID 34715925, 2021). "Several clinical trials are currently being conducted to evaluate the effectiveness of CTAs, such as NY-ESO-1, MAGE, MSLN, PRAME, PSCA, ROR2 and WT1, as treatment targets in breast cancers and other solid tumours." (PMID 34359776, 2021). "In conclusion, this is the first to report the prognostic significance of the co-expression of mesothelin and CA125 in breast cancer." (PMID 34715925, 2021). "The screening and selection of patients suitable for Mesothelin-targeting therapies on the basis of their Mesothelin expression in tumor biopsies is easy to perform and daily routine in other tumor entities (e.g. HER2/neu in breast cancer)." (PMID 32815024, 2020). "Subset analysis in breast cancer showed MSLN amplification rates of 28% in triple-negative breast cancer (TNBC) and 33% in basal-like breast cancer." (PMID 26172299, 2015). "Subtype analysis in breast cancer showed MSLN amplification rates of 28% in triple-negative breast cancer (TNBC) and 33% in basal-like breast cancer." (PMID 26172299, 2015). "We evaluated the expression of mesothelin and of basal markers in tissue microarrays of 226 TNBC and 88 non-TNBC and assessed the clinicopathologic features of mesothelin-expressing breast carcinomas." (PMID 25506917, 2014). "This trial enrolled 25 malignant pleural mesothelioma patients, 1 breast cancer patient, and 1 NSCLC patient and provided intrapleural administration of mesothelin-targeted chimeric antigen receptor (CAR) T cell therapy, which was shown to be safe and tolerable." (PMID 39682081, 2024). "In addition, two ongoing clinical studies in patients with advanced stage breast cancer employ CAR T cells targeting ErbB2 (Human Epidermal growth factor Receptor 2, HER2) and mesothelin." (PMID 36359405, 2022). "The co-expression of mesothelin and CA125 may be clinically useful for prognostication after surgical therapy in patients with breast cancer." (PMID 34715925, 2021). "Disruption of MSLN/MUC16 interaction by MesobsFab cannot explain this result because MUC16 expression has not been documented in breast cancer." (PMID 31354732, 2019). "MCF-7 is a human breast cancer cell line reported not to express MSLN on its surface." (PMID 29738555, 2018).
breast carcinoma (continued). "MSLN has been validated as a novel immunotherapy target for triple negative breast cancer, while LCN2’s role in promoting breast cancer progression and metastasis has been well-documented." (PMID 41139924, 2025).
gastric cancer (51 papers, 2012 to 2025). A primary or metastatic malignant neoplasm involving the stomach. "The tumor-associated cell surface antigen MSLN is an important therapeutic target, and MSLN overexpression has been reported in gastric cancer." (PMID 34671203, 2021). "We also examined the N-ERC/mesothelin concentrations in the supernatants of cultured cells and in the sera of gastric cancer patients using an enzyme-linked immunosorbent assay (ELISA)." (PMID 24146039, 2014). "Another study examining polymorphisms in the MSLN gene also demonstrated that certain mutations in the MSLN gene, such as rs3764247, were associated with a lower risk of gastric cancer and that patients harboring these mutations had significantly longer survival." (PMID 41400642, 2025). "Notably, MSLN appears to be associated with a favorable prognosis in patients with gastric cancer." (PMID 41400642, 2025). "For instance, MSLN-CAR-NK cells were found to be capable of specifically eliminating MSLN+ gastric cancer cells in vitro, while sparing MSLN-negative cells." (PMID 40650066, 2025). "Advances in solid tumor targeting continue to expand the repertoire of actionable antigens, including glypican-3 (GPC3) in hepatocellular carcinoma, Claudin18.2 in gastric cancer, mesothelin (MSLN), and B7-H3 across various malignancies." (PMID 41394856, 2025). "MSLN expression has been correlated with poor prognosis and resistance to chemotherapy in esophageal cancer and gastric cancer patients." (PMID 39417449, 2024). "Initially, they identified MSLN expression in 75 primary gastric cancer tissue samples and 20 normal gastric samples." (PMID 38694508, 2024). "Similar results were recently reported in a preclinical model of gastric cancer following peritumor injection of CAR-T cells targeting MSLN." (PMID 38570866, 2024). "Low levels of mesothelin expression in gastric cancer exhibited a notable correlation with both improved overall survival (OS) (p = .051) and disease‐free survival (DFS) (p = .067)." (PMID 39548594, 2024). "This is in line with prior studies using IHC that have shown mesothelin expression in approximately 47% of gastric cancer cases and about 30% of colorectal cancers." (PMID 39548594, 2024). "Mesothelin (MSLN) is a cell surface protein that is normally restricted to the mesothelial cells but is significantly overexpressed in esophageal and gastric cancer and others." (PMID 39417449, 2024). "In our previous study, we evaluated the feasibility of MSLN as a target of chimeric antigen receptor T cells for gastric cancer treatment." (PMID 34326835, 2021). "Collectively, these results demonstrate that MSLN expression was upregulated in both gastric cancer primary samples and cell lines." (PMID 34671203, 2021). "Then we evaluated MSLN expression in three human gastric cancer cell lines, including N87, MKN-28, and AGS, and one liver cancer cell line, Huh-7, by immunoblotting analysis." (PMID 34671203, 2021). "In BGC823 and MKN28 gastric cancer cell xenografts, sPH20-IgG2 promoted anti-mesothelin CAR-T cell infiltration into tumors." (PMID 34326835, 2021). "HA impeded in vitro anti-tumor activities of anti-mesothelin (MSLN) chimeric antigen receptor T cells (CAR-T cells) against gastric cancer cells by restricting CAR-T cell mobility in vitro." (PMID 34326835, 2021). "Our results showed that MSLN protein was highly expressed in xenografts of gastric cancer, so we tested the effect of MSLN-CAR NK cells in these PDX models." (PMID 34671203, 2021). "In the present study, we demonstrated potent and specific activity of MSLN-CAR NK-92 cells against MSLN-positive gastric cancer both in vitro and in vivo." (PMID 34671203, 2021). "We then seeded BGC823GL and KATOIIIGL gastric cancer cells that expressed mesothelin as target cells in the lower chamber, while HA was added to the upper chamber at different concentrations, and CAR-T cells were seeded in the upper chamber in the HA matrix." (PMID 34326835, 2021).
gastric cancer (continued). "Taken together, our results demonstrated that MSLN-CAR NK cells were able to efficiently suppress the growth of MSLN-positive gastric cancer PDX in vivo." (PMID 34671203, 2021). "In curatively resected stage III gastric cancer, MSLN expression is a significant predictive factor for peritoneal recurrence." (PMID 32780245, 2020). "In summary, we characterized mesothelin as an antigen of chimeric antigen receptor T cells in human gastric cancer, and utilized third-generation anti-Mesothelin CAR-T cell M28z10 to target human gastric cancer." (PMID 30777106, 2019). "Highest predicted MSLN amplification rate for gastrointestinal cancer was seen in pancreatic adenocarcinomas (36% of N = 121), followed by gastric cancers (24% of N = 212) and colorectal cancers (21% of N = 1,131)." (PMID 26172299, 2015). "The present study demonstrated that luminal membrane mesothelin expression is a reliable prognostic factor in gastric cancer." (PMID 25789005, 2015). "We evaluated the expression and extracellular secretion of ERC/mesothelin in human gastric cancer cell lines." (PMID 24146039, 2014). "ELISA detected N-ERC/mesothelin in 3 of the 6 studied gastric cancer cell lines; however, its concentration in the sera of gastric cancer patients was almost the same as that in the sera of the normal controls." (PMID 24146039, 2014). "We also examined the expression of C-ERC/mesothelin in cultured gastric cancer cell lines and human gastric cancer tissues by immunohistochemical staining." (PMID 24146039, 2014). "N-ERC/mesothelin was detected in the supernatants of 3 gastric cancer cell lines (MKN-1, NUGC-4 and TMK-1) by ELISA, but its concentration in the sera of gastric cancer patients was almost same as that observed in the sera of the normal controls." (PMID 24146039, 2014). "Several studies have detected C-ERC/mesothelin in human gastric cancer by immunohistochemical staining." (PMID 24146039, 2014). "In the present study, C-ERC/mesothelin positivity was detected in 5 of 6 gastric cancer cell lines (83.3%)." (PMID 24146039, 2014). "Conversely, in the gastric cancer tissues, C-ERC/mesothelin expression was associated with lymphatic invasion." (PMID 24146039, 2014). "Two of these 3 studies examined the clinicopathological features and C-ERC/mesothelin expression in gastric cancer." (PMID 24146039, 2014). "To evaluate whether anti-MSLN CAR-like NK cells can inhibit distant tumor metastasis in gastric cancer, we established a lung metastasis mouse model by intravenously injecting MKN45 cells into mice." (PMID 41436559, 2025). "Additionally, mesothelin has emerged as a potential target tumor antigen for ovarian, pancreatic, breast, and gastric cancers." (PMID 38694508, 2024). "The observed correlation between mesothelin expression and survival in gastric cancer may be used as a prognostic biomarker for this tumour." (PMID 39548594, 2024). "Anti-MSLN-SP CAR-T cells can shrink tumors better in a gastric cancer PDX model." (PMID 39023820, 2024). "The coexpression of sPH20-IgG2 (the secreted form of PH20) significantly enhanced the ability of anti-MSLN CAR-T cells to degrade HA in the treatment of gastric cancer with high MSLN expression; moreover, the infiltration efficiency of anti-MSLN-SP CAR-T cells in solid tumor tissues was improved." (PMID 39023820, 2024). "Our results indicated that the expression levels of mesothelin was closely associated with the survival rate of patients with gastric cancer but not with colon carcinoma." (PMID 39548594, 2024). "A phase I clinical trial conducted by Chinese PLA General Hospital (NCT03747965) is currently evaluating the feasibility and safety of CRISPR-Cas9 mediated PD-1 gene-knockout CAR-T cells in patients with MSLN-positive multiple solid tumors, including esophageal cancer and gastric cancer." (PMID 39417449, 2024).
gastric cancer (continued). "Our results also show that lower mesothelin expression is associated with increased overall survival in gastric carcinomas but not colon carcinoma." (PMID 39548594, 2024). "Furthermore, some of them have been proven to be drug targets in solid tumors, such as GPC3 in liver cancer, MSLN in gastric cancer, and EGFR in glioma." (PMID 36428765, 2022). "Our results suggested that MSLN-targeted NK cell therapy represent a clinically appealing treatment strategy for gastric cancer patients with positive MSLN expression, thus providing the basis for additional investigations in the clinical application of immunotherapy against gastric cancer." (PMID 34671203, 2021). "The results of this assay demonstrated that HA could significantly decrease the killing activity of anti-MSLN CAR-T cells against both gastric cancer cell lines at each E:T ratio, and this effect was positively correlated with the concentration of HA." (PMID 34326835, 2021). "It has been reported that mesothelin (MSLN) may be an ideal immunotherapy target for gastric cancer." (PMID 34671203, 2021). "In this study, we established three MSLN-positive gastric cancer PDX models through NSG mice." (PMID 34671203, 2021). "Our results suggest that mesothelin may be a potential target of CAR T cells for treating gastric cancer." (PMID 30777106, 2019). "Furthermore, the localization of mesothelin in gastric cancer, extrahepatic bile duct cancer and colorectal adenocarcinoma was also investigated in each study." (PMID 25789005, 2015). "Other factors such as protease activity may also be responsible for the lower serum N-ERC/mesothelin levels experienced in gastric cancer cases." (PMID 24146039, 2014). "Therefore, in the present study we evaluated the expression and extracellular secretion of ERC/mesothelin in human gastric cancer tissues and cell lines derived from gastric cancer." (PMID 24146039, 2014). "In the gastric cancer tissues, C-ERC/mesothelin expression was associated with lymphatic invasion." (PMID 24146039, 2014). "In addition, C-ERC/mesothelin positivity was observed in human gastric cancer tissues from 29 of the 50 cases (58%)." (PMID 24146039, 2014). "However, accumulating evidence from other studies suggests that MSLN may portend a poor prognosis for patients with gastric cancer." (PMID 41400642, 2025). "To detect MSLN expression in gastric cancer tissue, we performed immunohistochemical staining for MSLN in 75 primary gastric cancer and 20 normal gastric samples and found robust expression in 54.7% (41/75) of gastric cancer samples, but negatively found in normal gastric tissue (data not shown)." (PMID 34671203, 2021). "To further validate the enhanced function of anti-MSLN CAR-like NK cells in a systemic environment, we conducted experiments using the NCI-N87 gastric cancer subcutaneous tumor model." (PMID 41436559, 2025). "In esophageal and gastric cancers, targets such as HER2 (NCT02713984), EGFR, CEA (NCT02349724), MSLN (NCT03747965), CLDN18.2 (NCT05472857), and NKG2D have shown effective antitumor effects in preclinical and early clinical trials." (PMID 40909948, 2025). "The mesothelin (MSLN) protein, prevalent in normal mesothelial tissues and markedly overexpressed in gastric cancers, has also been a target for CAR-T therapies." (PMID 40028336, 2025). "Studies have indicated that antigens like HER2, CEA, MUC1, Claudin 18.2 (CLDN 18.2), EpCAM, B7H3, MSLN, and NKG2D serve as effective targets for CAR-T cell therapy in gastric cancer." (PMID 38622705, 2024). "Gastric cancer cell lines AGS, N87, and HGC27, along with colorectal cancer cell lines SW48 and HTB39, tested positive for MSLN expression." (PMID 39548594, 2024). "Mouse models of gastric cancer have shown promising anti-tumor activity of CAR-NK cells, such as with mesothelin-specific CAR-NK cells." (PMID 36497422, 2022).